C2CD3 (C2 domain containing 3 centriole elongation regulator)
Description:
Component of the centrioles that acts as a positive regulator of centriole elongation. Promotes assembly of centriolar distal appendage, a structure at the distal end of the mother centriole that acts as an anchor of the cilium, and is required for recruitment of centriolar distal appendages proteins CEP83, SCLT1, CEP89, FBF1 and CEP164. Not required for centriolar satellite integrity or RAB8 activation. Required for primary cilium formation. Required for sonic hedgehog/SHH signaling and for proteolytic processing of GLI3.
Synonyms: DKFZP586P0123; OFD14
Tractability: PROTAC: ubiquitination databases record sites on it.
Gene: Protein-coding gene on chromosome 11 (74,012,718 to 74,171,210, reverse strand). Ensembl gene ENSG00000168014.
Subcellular location: Cytoplasm, cytoskeleton, cilium basal body; Cytoplasm, cytoskeleton, microtubule organizing center, centrosome, centriole
Subcellular location (Human Protein Atlas): Basal body; Centrosome; Nucleoplasm; Acrosome; Equatorial segment; Principal piece
Pathways (Reactome):
Organelle biogenesis and maintenance: Anchoring of the basal body to the plasma membrane
Gene Ontology:
Molecular function: protein binding
Biological process: centriole elongation; non-motile cilium assembly; protein localization to centrosome; cilium assembly
Cellular component: centriolar satellite; centriole; centrosome; ciliary basal body; cytosol; microtubule organizing center
Genetic constraint (gnomAD): Loss-of-function variants: 102 observed, 188.84 expected, observed/expected ratio (o/e) 0.54, 90% interval 0.46 to 0.64. The upper end of that interval is the gene's LOEUF score, 0.64, which puts it in group 2 of 6, group 1 being the genes least tolerant of losing a copy. Missense variants: 2,174 observed, 2,535.4 expected, observed/expected ratio (o/e) 0.86, 90% interval 0.83 to 0.89. Synonymous variants: 871 observed, 946.34 expected, observed/expected ratio (o/e) 0.92, 90% interval 0.87 to 0.97.
Gene-disease validity (ClinGen):
ClinGen rates the evidence that C2CD3 causes each of these diseases.
orofaciodigital syndrome type 14 (autosomal recessive): Definitive.
Homologues: Orthologues: chimpanzee C2CD3 (97% identical), macaque C2CD3 (96% identical), dog C2CD3 (84% identical), rabbit C2CD3 (83% identical), guinea pig C2CD3 (79% identical), pig C2CD3 (78% identical), mouse C2cd3 (76% identical), rat C2cd3 (75% identical), tropical clawed frog c2cd3 (44% identical), zebrafish c2cd3 (37% identical), Drosophila melanogaster CG32425 (8% identical).
Diseases named in the same sentence as C2CD3 in open-access papers:
C2CD3 is named in the same sentence as 12 diseases in open-access papers, as found by Europe PMC text mining. Sharing a sentence is not in itself a finding about the gene and the disease. The quoted sentences say what the papers report.
ciliopathies (10 papers, 2014 to 2025). "The protein C2CD3 is critical for distal appendage assembly, with mutations linked to orofaciodigital syndrome and other ciliopathies." (PMID 41364719, 2025). "Mutations in human C2CD3 are associated with the human ciliopathy Oral-Facial-Digital syndrome type 14 (OFD14)." (PMID 34211969, 2021). "While several other centriolar proteins are required for centriole maturation, elongation, and uncapping, C2cd3 and Ofd1 have been a focus of study because of their association with the human ciliopathy Oral-facial-digital syndrome (OFD)." (PMID 34211969, 2021). "The microtubule-binding protein SAS-1 is homologous to the human ciliopathy component C2CD3 and contributes to centriole integrity in C. elegans, but how this function is exerted is incompletely understood." (PMID 41124206, 2025). "Together, these insights significantly expand our understanding of centriole architecture and maturation, and position C2CD3 as a multifunctional scaffold with relevance to both centriole biology and ciliopathy mechanisms." (PMID 41364719, 2025). "Together, through generation of novel models and evaluation of C2cd3 expression, these data provide valuable insight into mechanisms of pathology for craniofacial ciliopathies that can be further explored in the future." (PMID 34211969, 2021). "Mouse C2cd3 mutants display phenotypes reminiscent of human ciliopathies, including severe polydactyly, situs defects, and disruption of the dorsal–ventral patterning of the neural tube." (PMID 27114821, 2016). "Interestingly, five of the potential interactors (PIBF1, CSPP1, OFD1, C2CD3, and KIF7) have been linked to a single ciliopathy, the Joubert syndrome, reinforcing the role of CCP6 activity in cilia regulation." (PMID 36674791, 2023). "Together, our findings reveal a novel role of CEP120 in ciliogenesis by showing that it interacts with C2CD3 and Talpid3 to assemble centriole appendages and by illuminating the molecular mechanism through which the CEP120 (I975S) mutation causes complex ciliopathies." (PMID 30988386, 2019). "The C2CD3 ortholog in humans is in the HSA11q13.4 chromosomal region, in close proximity to the critical regions for other human ciliopathies, including Meckel-Gruber syndrome 2 (MKS; 603194), Joubert syndrome 2 (JBTS2; 608091) and Nephronophthisis 15 (NPHP15; 614845)." (PMID 25053433, 2014). "In order to better understand the etiology of ciliopathies including OFD14, we generated numerous murine models targeting C2cd3." (PMID 34211969, 2021). "We herein showed that CEP120 directly interacts with C2CD3 and Talpid3, making it particularly notable that mutations in all three encoding genes reportedly give rise to a similar spectrum of ciliopathies, including the overlapping clinical features of JS and JATD26,27,50–53." (PMID 30988386, 2019). "C2CD3 is essential for craniofacial development and skeletal patterning, and its dysfunction leads to skeletal dysplasia and oral-facial-digital (OFD) syndromes, ciliopathies marked by defects in the face, oral cavity, and limbs." (PMID 41364719, 2025).
Joubert syndrome (2 papers, 2019 to 2023). Joubert syndrome (JS) is characterized by congenital malformation of the brainstem and agenesis or hypoplasia of the cerebellar vermis leading to an abnormal respiratory pattern, nystagmus, hypotonia, ataxia, and delay in achieving motor milestones. "Finally, recent reports showed that mutations in the C2CD3 gene cause skeletal dysplasia, polydactyly, and ciliopathies, while Talpid3 mutations cause Joubert syndromes and Short-Rib polydactyly syndromes." (PMID 30988386, 2019). "Intriguingly, five of the candidate interactors found in our BioID-based interactomic study (i.e., C2CD3, PIBF1, CSPP1, OFD1, and KIF7) are related to a single rare pathology, the Joubert syndrome." (PMID 36674791, 2023).
oral-facial-digital syndrome (2 papers, 2016 to 2025). "Ofd1, a protein mutated in oral-facial-digital syndrome, co-localizes with C2cd3 at the distal centriole." (PMID 27114821, 2016).
COVID-19 (1 paper, 2022). A disease caused by infection with severe acute respiratory syndrome coronavirus 2. "In this study, we found 14 other diseases associated with COVID-19 by sharing four DEGs (i.e., DMD, C2CD3, WNT3, and AHDC1) most prevalent in COVID-19." (PMID 36059456, 2022). "In addition, we identified 14 other diseases associated with COVID-19 by sharing four DEGs (i.e., DMD, C2CD3, WNT3 and AHDC1) which were most prevalent in COVID-19." (PMID 36059456, 2022).
developmental delay (1 paper, 2020). "Four genes (UCP2, UCP3, SCAPER, and TSHR) are related to the body weight (HP:0004324 and HP:0004323), and four genes (C2CD3, UCP2, ZMYND11, and TSHR) are involved in modulating the phenotype of globe developmental delay (HP:0001263)." (PMID 32973871, 2020).
microcephaly (1 paper, 2016). A congenital or acquired developmental disorder in which the circumference of the head is smaller than normal for the person's age and sex. "Recently, mutations in the gene encoding the centriolar protein C2CD3 have been described in two families with a new sub-type of OFDS (OFD14), with microcephaly and cerebral malformations." (PMID 27094867, 2016).
C2CD3 also shares sentences with these, for which no sentence is quoted: skeletal dysplasia (2 papers); Meckel-Gruber syndrome (1); nephronophthisis (1); Oral-Facial-Digital syndrome type 14 (1); orofaciodigital syndrome (1); polydactyly (1).